CXCR4 (C-X-C motif chemokine receptor 4)
Diseases named in the same sentence as CXCR4 in open-access papers (continued):
Sharing a sentence is not in itself a finding about the gene and the disease.
psoriasis (18 papers, 2014 to 2026). An autoimmune condition characterized by red, well-delineated plaques with silvery scales that are usually on the extensor surfaces and scalp. "Finally, the CXCR4/CXCL12 signaling axis plays a pivotal role in numerous biological processes and an overexpression of CXCR4 has been associated with several diseases including skin inflammatory diseases such as psoriasis and AD." (PMID 34912758, 2021). "A study aimed at developing a CXCR4 inhibitor suitable for topical use in treating psoriasis to minimize systemic toxicity." (PMID 39070795, 2024). "Both CXCL12 inhibition and CXCR4 antagonism ameliorated psoriasis-like lesions in IMQ-treated mice, including epidermal thickness, and proportion of infiltrating Ly6G+CXCR4hi neutrophils." (PMID 37736772, 2023). "We suggest extending such trials based on exploiting the CXCR4 mediated dysregulation of the immune system to other IMIDs like psoriasis, CD, RA, and UC." (PMID 34108969, 2021). "We propose that CXCR4/SDF-1 is an important skin-homing mechanism under inflammatory conditions in psoriasis." (PMID 28303135, 2017). "In this study, we investigated the role of the SDF-1/CXCR4 axis in human psoriasis and in experimental chronic skin inflammation." (PMID 24695674, 2014). "To investigate the role of the SDF-1/CXCR4 axis in a second mouse model of psoriasis, we used the imiquimod-induced psoriasis-like skin inflammation model." (PMID 24695674, 2014). "Firstly, we observed increased surface expression of CXCR4 on peripheral psoriatic neutrophils compared with healthy controls as measured by mean fluorescence intensity (MFI) of CXCR4, which was positively correlated with Psoriasis Area Severity Index (PASI) (R = 0.37, p = 0.0012, n = 25)." (PMID 37736772, 2023). "Notably, in psoriasis patients treated with an anti-interleukin (IL)-17A biologic (secukinumab), CXCR4 expression on circulating neutrophils was reduced over a 12-weeks period treatment and was concomitant with a decrease in overall disease activity." (PMID 37736772, 2023). "CXCR4 is expressed by basal keratinocytes, but its role in psoriasis is still poorly understood." (PMID 33613635, 2021). "Other reports have shown a beneficial role of the CXCL12/CXCR4 axis in psoriasis." (PMID 31507535, 2019). "In this report, we propose that CXCR4-SDF-1 is an alternative mechanism in psoriasis (and inflammatory conditions), which may explain the presence of ILC and cytokine production in psoriasis patients even in the absence of CCL27." (PMID 28303135, 2017). "Based on the reported elevated mRNA levels of the angiogenic chemokine stromal cell-derived factor-1 (SDF-1) and its receptor CXCR4 in psoriasis, we investigated the relevance of the SDF-1/CXCR4 axis in two experimental models of chronic psoriasis-like skin inflammation." (PMID 24695674, 2014). "We first investigated whether CXCR4 might play a role in human psoriasis." (PMID 24695674, 2014). "Namely, the previously published studies investigated the molecular interaction of quercetin and psoriasis genes CXCL2 and CXCR4, as well as Src family tyrosine kinases (SFKs)." (PMID 40806422, 2025). "Both CXCR4 and CXCL14 show significantly elevated expression in all psoriasis-related conditions compared to normal skin." (PMID 40351602, 2025). "As a result, immunostimulatory genes showed higher expression levels within psoriasis than normal tissues, such as CD86, CD48, TNFRSF4, TNFRSF25, ICOS, and CXCR4." (PMID 36685512, 2022). "Consistently, spatial transcriptomics localized CXCR4 expression within sarcoid granulomas, and expression was minimal or not seen in patients with psoriasis or healthy unaffected skin." (PMID 39225100, 2024). "The CXCL12/CXCR4 pathway is known to be involved in chronic skin inflammatory diseases such as psoriasis; however, its effects on hair inflammation have not been studied." (PMID 38338982, 2024).
psoriasis (continued). "Importantly, both the Lin− CD123low and CD127+ populations were increased in the skin of psoriasis patients; however, it is possible that the CD127+ ILC may migrate by a mechanism independent of CXCR4/SDF-1 but CCR6-dependent because high levels of CCR6 were identified in the CD127+ ILC population." (PMID 28303135, 2017).
clear cell renal cell carcinoma (17 papers, 2008 to 2025). "Research has indicated that PGK1 enhances glycolysis via CXCR4/ERK pathway activation, which is associated with sorafenib resistance in clear cell renal cell carcinoma." (PMID 40786054, 2025). "For example, phosphoglycerate kinase 1 (PGK1) plays a role in the development of renal clear cell carcinoma and resistance to sorafenib by activating the C-X-C motif chemokine receptor 4 (CXCR4)/ERK pathway, thereby accelerating glycolysis." (PMID 40837407, 2025). "Generally, PGK1 upregulation contributes to tumorigenesis and sorafenib resistance of renal clear cell carcinoma via activating CXCR4/ERK signaling pathway and accelerating glycolysis." (PMID 35121728, 2022). "Compared to healthy renal cells, the expression of CXCR4 is significantly increased in clear cell renal cell carcinoma, and this increased expression is significantly correlated with tumor stage or grade, thus indicating significant predictive value." (PMID 34496868, 2021). "For squamous cell carcinoma of the lung and clear cell renal cell carcinoma, frequencies of CXCR4+ cases were significantly higher in metastatic versus primary cancers, with P= 0.01 and P=0.02, respectively." (PMID 29088715, 2017). "Loss of PRC2-mediated histone H3K27me3 activates hypoxia-inducible transcription factors (HIF)-driven expression of chemokine (C-X-C motif) receptor 4 (CXCR4), leading to metastasis of clear cell renal carcinoma (ccRCC) cells." (PMID 28561778, 2017). "It is of interest, therefore, that we found higher frequencies of CXCR4+ samples from metastatic as compared with primary tumors for squamous cell cancer of the lung and clear cell renal cell cancer." (PMID 29088715, 2017). "Furthermore, a prognostic value of positive cytoplasmic CXCR4 expression is emerging in clear cell renal cell carcinoma." (PMID 36982302, 2023). "For renal cell clear cell carcinoma, where we had matched primary and metastatic samples, our data are consistent with preferential metastasis by CXCR4+ primary cancers as a basis for the enrichment of CXCR4+ cases among the metastases, which is in line with some published findings." (PMID 29088715, 2017). "Therefore, CXCR4 might be an interestingtherapeutic target in a multimodal therapy of renal clear cell carcinoma." (PMID 19266088, 2008). "X4P-001-IO, a CXCR4 inhibitor, in combination with axitinib has exhibited a promising disease control rate (DCR) of 93% in clear cell renal cell carcinoma, which was announced by Atkins' team." (PMID 31219799, 2019).
head and neck squamous cell carcinoma (17 papers, 2009 to 2024). A squamous cell carcinoma that arises from any of the following anatomic sites: lip and oral cavity, nasal cavity, paranasal sinuses, pharynx, larynx, and salivary glands. "It has been confirmed that patients with overexpression of CXCR4 have a worse prognosis for head and neck squamous cell carcinoma; thus, it is urgent and necessary to find new therapeutic approaches targeting CXCR4." (PMID 38066523, 2023). "Examination of the TCGA database unveiled positive correlations between PA28γ expression and both CD44 and CXCR4 expression in the head and neck squamous cell carcinoma (HNSCC) cohort." (PMID 38721005, 2024). "In head and neck squamous cell carcinomas (HNSCC), as in many other cancer types, the CXCL12/CXCR4 axis is involved in metastatic dissemination." (PMID 32296435, 2020). "TWIST seems to be a pivotal transcription factor that may positively regulate the expression of CXCR4 and CCR7 genes during lymph node metastasis, and its expression is significantly correlated with the clinical stage of head and neck squamous cell carcinoma." (PMID 21743395, 2012). "Both IFNs have anti-angiogenic activities and significantly repress CXCR4 gene expression that can lower the vascularity surrounded NMSC and impact in SDF-1-induced cell migration and proliferation of CXCR4-positive cells as have been demonstrated in head and neck squamous cell carcinomas for IFN-γ." (PMID 19643007, 2009).
nasopharyngeal carcinoma (17 papers, 2005 to 2024). A carcinoma arising from the nasopharyngeal epithelium. "In the present study, we evaluated CXCR4 expression in nasopharyngeal carcinoma by immunohistochemistry." (PMID 15978137, 2005). "In this study, we investigated the expression of CXCR4 in nasopharyngeal carcinoma (NPC) tissues by immunohistostaining." (PMID 15978137, 2005). "Previous studies revealed that TPST1 could sulfate the tyrosine of C-X-C motif chemokine receptor (CXCR4) and the tyrosine sulfation might contribute to nasopharyngeal carcinoma metastasis." (PMID 30662454, 2018). "Recent studies have indicated that the expression of endothelin A receptor (ETAR) and chemokine receptor 4 (CXCR4) could be used as an indicator of the metastatic potential of nasopharyngeal carcinoma (NPC)." (PMID 23987636, 2013). "In nasopharyngeal carcinoma (NPC) cells, CXCL12 effectively attracted CXCR4+ Treg cells." (PMID 37497001, 2023). "Antagonism of CXCR4/CXCR7-CXCL12 downregulated the expression of the chemokines axis and therefore could be used to control and potentially even cure nasopharyngeal cancer." (PMID 36140541, 2022). "In our previous study, both metastatic and nonmetastatic nasopharyngeal carcinoma cell lines express CXCR4 at the mRNA and protein levels, but functional CXCR4 is only found in cell lines with metastatic properties." (PMID 23472069, 2013). "Several CXCR4 antagonists have been tested using HNSCC cell lines, and the results show that antagonism of CXCR4/CXCR7-CXCL12 downregulates the expression of the chemokines axis and, therefore, could be used to control and potentially even cure nasopharyngeal cancer." (PMID 39001265, 2024).
sarcoma (17 papers, 2010 to 2024). A usually aggressive malignant neoplasm of the soft tissue or bone. "In a recent meta-analysis of 12 studies including a total of 997 sarcoma patients, CXCR4 expression was found to be significantly associated with poor overall survival, higher rates of metastasis and higher tumor stage." (PMID 31428099, 2019). "The targeting of CXCR4 mRNA by miR-146a was confirmed also by other studies showing that the Kaposi's sarcoma-associated hepesvirus-encoded viral FLICE inhibitor protein (v-FLIP) mediates CXCR4 suppression through miR-146a upmodulation." (PMID 22453030, 2012). "The chemokine receptor CXCR4 has been implicated in sarcoma development and has been found to be a prognostic marker for poor clinical outcome." (PMID 21234386, 2011). "We will also discuss the role of Ephrin receptors, Hippo pathway, BET proteins and CXCR4 signaling, as mediators of sarcoma malignancy and relevant interactors with the IGF system in tumor cells." (PMID 34440844, 2021). "The synergy between NK cell antimetastatic function and inhibition of prometastatic CXCR4 on sarcoma cells resulted in the elimination of primary tumors as well as micro- and macrometastases in mice." (PMID 33322371, 2020). "We analyzed the surface expression of CXCR4 on confluent cultures of various sarcoma cell lines: RH30, CW9019, A4573, A673, MG-63, and 143B." (PMID 31428099, 2019). "We assessed the antitumor potential of MDX1338 and NKAE cell therapies, by generating an in vivo model of metastatic sarcoma, using CXCR4+ RH30 cells, which grow as peritoneal xenografts when implanted in immunodeficient NSG mice." (PMID 31428099, 2019). "The CXCL12/CXCR4 axis showed an intense coexpression in both sarcomas at all times throughout the experience." (PMID 28386296, 2017). "Although further investigation is necessary to validate these pathways, there is potential for clinical application, particularly in the use of pharmacologic inhibitors of CXCR4 as means of preventing sarcoma metastasis." (PMID 21234386, 2011). "Among these recent discoveries is the role that the chemokine receptor CXCR4 plays in the pathogenesis of several subtypes of sarcoma." (PMID 21234386, 2011). "Data are discussed that imply CXCR4 inhibitors as promising add-ons to classical chemotherapy to prevent deadly metastases in sarcoma patients." (PMID 21772794, 2011). "CXCR4 plays an important role in tumor progression and metastases of several sarcoma subtypes." (PMID 34440844, 2021). "Additionally, hypoxia-inducible factor 1-alpha (HIF-1α) increases CXCR4 expression on sarcoma cells, contributing to metastasis development." (PMID 33322371, 2020). "Notably, in sarcoma patients, increased HIF-1α and CXCR4 expression are associated with advanced disease." (PMID 33322371, 2020). "Thus, our findings provide first evidence for a signaling crosstalk between CXCR4 and RTKs with pro-tumorigenic potential in pediatric sarcomas." (PMID 29776413, 2018). "Finally, in vivo data indicate the potential of CXCR4 as a target for chemotherapy agents and the possible use of CXCR4 inhibitors in preventing the development of metastasis from sarcomas." (PMID 21234386, 2011). "In our model, we hypothesize that MDX1338 blocks not only metastatic CXCR4+ sarcoma cells migration to the lungs, but also blocks therapeutic NKAE cells homing to the bone marrow and favors their permanence in the blood stream, where they are more likely to find and kill metastatic neoplastic cells." (PMID 31428099, 2019). "We present preclinical data showing the ability of NKAE cell therapy to kill sarcoma cells and of MDX1338 mAb to inhibit the migration and invasion of CXCR4+ sarcoma cells in vitro." (PMID 31428099, 2019). "There is evidence that CXCR4 and its ligand, CXCL12, play a critical role in the preferential targeting of sarcoma metastases towards lung and bone." (PMID 21234386, 2011).
sarcoma (continued). "CXCR7 is one of the receptors for CXCL12 other than CXCR4, therefore the CXCL12-CXCR7 axis might be involved in sarcoma development through tumor cell and stromal cell interaction." (PMID 22852096, 2012). "As previously revealed data were achieved using animal model, sarcoma cell lines and molecular evaluation, our study has been more focused on the protein expression levels of two CSC markers CD133 and CXCR4 using immunohistochemical detection in the human OS tissues." (PMID 31983166, 2020).
adenoma (16 papers, 2012 to 2026). A neoplasm arising from the epithelium. "More recently, CXCR4 expression has been used as a marker and potential therapeutic target in adrenal cancer, as well as for clinical diagnostic imaging of aldosterone-secreting adenomas using 68Ga-pentixafor PET/CT." (PMID 37440461, 2023). "CXCR4 is highly expressed in the zona glomerulosa and in aldosterone-producing adenomas, and it closely correlates with CYP11B2 (aldosterone synthase) expression." (PMID 41991734, 2026). "C-X-C motif chemokine receptor 4 (CXCR4) is highly expressed in aldosterone-producing adenoma, and gallium-68 pentixafor PET-CT imaging targeting CXCR4 has been utilized for subtype diagnosis in primary aldosteronism." (PMID 42290661, 2025). "In this study, we observed a strong co-localization of aldosterone synthase (CYP11B2) and CXCR4 in aldosterone-producing adenoma and other aldosterone-producing lesions." (PMID 42290661, 2025). "CXCR4, a cancer stem cell marker in several tumors, inclusively in corticotroph adenomas, was higher expressed in FCA." (PMID 33066652, 2020). "Histological analysis revealed that CXCR4+/−Apcmin/+ mice exhibited larger adenomas with atypical dysplasia than Apcmin/+ mice." (PMID 30678736, 2019). "AOM/DSS-treated CXCR4+/− mice exhibited much larger adenocarcinomas with disordered crypt structure and glandular lumens than WT mice carrying micro-adenomas with atypical dysplasia." (PMID 30678736, 2019). "AMD3100 significantly attenuated AOM/DSS-induced adenocarcinoma and restored to organized crypts and small adenoma in CXCR4+/− mice." (PMID 30678736, 2019). "CXCR4+/−Apcmin/+ mice treated with 3 cycles of DSS developed dramatically more adenomas than their littermate Apcmin/+ mice at age of 30 weeks." (PMID 30678736, 2019). "Compared with Apcmin/+ mice, where the location of adenomas is almost exclusively in small intestine, CXCR4+/−Apcmin/+ mice exhibited more tumor load in colon at age of 30 weeks in addition to the increased adenoma in small intestine." (PMID 30678736, 2019). "Several mechanisms by which CXCL12/CXCR4 modulates pituitary function and promotes adenoma cell proliferation and their target as potential therapeutic approach have been suggested." (PMID 25484899, 2014). "CXCL12 is overexpressed in pituitary cells where it can directly influence adenoma formation, through autocrine mechanisms resulting in constitutive CXCR4 activation." (PMID 25484899, 2014). "High CXCR4 expression has also been demonstrated in cortisol-producing adenomas." (PMID 40246740, 2025). "Notably, CXCR4+/−Apcmin/+ compound mutant mice develop on average 43 polyps and 5 adenomas per colon." (PMID 30678736, 2019). "Work by Mertens and coworkers reported the identification of a side population within human adenomas that, when purified of endothelial and immune cells, expressed stemness markers such as SOX2, NESTIN and CXCR4 and epithelial–mesenchymal transition-linked factors." (PMID 28855316, 2018). "Recently, several studies have revealed the expression of CXCL12 and/or CXCR4 in human pituitary tumors, suggesting that this chemokine may act as a promoting factor for adenoma development." (PMID 26441831, 2015). "However, the majority of studies focused on the analysis of CXCL12 and CXCR4 expression in human neoplastic pituitary tissues and their role in adenoma cell proliferation." (PMID 25484899, 2014). "Interestingly, in few adenomas, the blockade of CXCR4 with AMD3100, a known CXCR4 antagonist, caused, beside the abolishment of CXCL12-mediated increase in cell proliferation, also a reduction of basal DNA synthesis." (PMID 25484899, 2014). "CXCR4 is a typical member of the GPCR family, which may explain why 68Ga-pentixafor uptake occurs in cortisol-producing adenomas." (PMID 40246740, 2025).